INSR (insulin receptor)
Diseases named in the same sentence as INSR in open-access papers (continued):
Sharing a sentence is not in itself a finding about the gene and the disease.
tumor (continued). "Interestingly, in all tumour tissues expression of INSR was rather exclusively observed in the vasculature." (PMID 30559346, 2019). "Furthermore these receptors by binding insulin receptor substrate molecules promoted tumor cells proliferation, differentiation and metastasis, and simultaneously inhibited apoptosis." (PMID 30299268, 2018). "However, 7 new gene sets were associated with tumor suppressors or metabolic pathways upregulated by the panobinostat/JQ1 combinatorial treatment, such as the biosynthesis of antibiotics, insulin receptor signaling pathway, and FoxO signaling pathway." (PMID 30285808, 2018). "Interestingly, we found a significant and sevenfold downregulation of the B-isoform of the insulin receptor in MG tumor tissue compared to normal MG tissue." (PMID 28173837, 2017). "Tumor characteristics and treatments in relation to tumor-specific expression of nuclear InsR." (PMID 29234306, 2017). "In this study, we hypothesized that the prognostic value of tumor-specific nuclear InsR expression may differ according to the patients’ BMI, tumor ER status, as well as type of adjuvant treatment." (PMID 29234306, 2017). "Thus, INSR functionally enhances multistage tumor progression and conveys intrinsic resistance to IGF1R targeted therapyin pancreatic islet tumor growth." (PMID 27861515, 2016). "Insulin receptor expression may lead to a compensatory mechanism for tumor treated with IGF-1R targets agents." (PMID 26217584, 2015). "Furthermore, it is able to modulate the metabolism of glucose and lipids by indirectly regulating insulin receptor protein expression, which has been demonstrated to be important for tumor initiation and development." (PMID 25199534, 2014). "In humans, insulin may enhance tumor progression via the INSR, while insulin analogs with INSR dissociation rates slower than insulin may have greater mitogenic activity." (PMID 24533136, 2014). "On the other hand, INSR targeting could be potentially advantageous, because specific inhibition of the INSR in the tumor might increase the effective anti-tumoral activity." (PMID 24904527, 2014). "Finally, treatment with the dual IGF-IR/InsR inhibitor AZD9362 enhanced the anti-tumor effect of AZD5363 in MCF-7/LTED cells and MCF-7 xenografts in ovariectomized mice devoid of estrogen supplementation." (PMID 23844554, 2013). "Functional imaging like FDG–PET may lead to a false negative result due to accelerated uptake of FDG by skeletal and cardiac muscles as these tissues have a much higher expression of insulin receptor when compared with the tumor tissue." (PMID 24616774, 2013). "Thus, while we cannot entirely rule out an increase in INSR activation in the IGF1R deficient tumor models, there is not a compensatory increase in expression of the INSR." (PMID 36568144, 2022). "Insulin and its analogues may function as growth factors and therefore have a theoretical potential to promote tumor proliferation through various mechanisms involving activation of the insulin receptor, IGF-1 receptor (IGF-1R) and extracellular-signaling-regulated kinase (ERK) pathways." (PMID 34535145, 2021). "When the tumor grew on the right hemisphere, local efficiency (p < 0.001) and shortest path length (p = 0.001) were significantly increased and global efficiency was significantly decreased (p = 0.001) in the insR group as compared with those in the control group." (PMID 33436741, 2021).
tumor (continued). "ENPP4 showed a catalytic domain in Asp192, His196, His339 Asp37, Thr73, Asp240, and His241, which suggests that the ENPP4 may affect some receptor such as ATP receptor or insulin receptor on the surface of tumor cells to reduce their proliferation by indirectly or directly contact, receptively." (PMID 26823374, 2016). "In addition to the challenges associated with the development of most inhibitors, including specific tumor delivery and dose-related issues, the large homology that exists between this receptor and the related INSR should be taken into account while developing IGF1R inhibitors." (PMID 24434591, 2014). "The insulin-lowering effects of metformin may play a major role in its anticancer activity since insulin has mitogenic and prosurvival effects and tumor cells often express high levels of the insulin receptor, indicating a potential sensitivity to the growth promoting effects of the hormone." (PMID 21470407, 2011). "Similarly atypical teratoid/rhabdoid tumours of the CNS over-express the insulin receptor." (PMID 20436918, 2010). "C-myc targets INSR and IGF1R, which promoting tumor occurrence and metastasis in TSCC via NF-κB pathway." (PMID 38586328, 2024). "In conclusion, CREB3 acted as a tumor suppressor in HCC, which inhibited AKT phosphorylation through independently interfering interaction of INSR with IRS1, and transcriptionally activating RBM38." (PMID 38952575, 2024). "IGF2 promotes tumor growth through its interaction with the IGF1 receptor (IGF1R) and the insulin receptor (IR), triggering downstream signaling pathways that drive oncogenesis." (PMID 39682247, 2024). "It was demonstrated, for the first time, that the abundance of EGFR, INSR, VGFR3 and AXL, is lower in tumours relative to livers from healthy individuals whilst the opposite is true for IGF1R." (PMID 36890818, 2023). "We obtained five cell subpopulations, including four clusters (C0, C1, C2, C4) of tumor endothelial cells (PLVAP, VWA1, HSPG2, and INSR) and lymphatic endothelial cells (C3) (PDPN, CCL21)." (PMID 37715019, 2023). "A recent study found that erlotinib-resistant CCA cells highly expressed insulin receptor (IR) and insulin-like growth factor (IGF) 1 receptor (IGF1R), and In vivo tumor formation model constructed from these resistant cells showed rich CAFs infiltration." (PMID 35971182, 2022). "On the other hand, we observed the significant upregulation of the insulin receptor gene (ISNR), which is responsible for stimulation of tumor cell proliferation, migration, and invasion, and can be co-expressed with the EGFR gene in tumors." (PMID 35216085, 2022). "The mechanism of action is represented by the inhibition of the autophosphorylation of ALK gene and the molecular targets include IGF-1 R, InsR, and ROS1 and have an activity of 20 times higher against crizotinib–resistant tumor cell lines." (PMID 34082691, 2022). "The expressions of INSR, IRS-1, and PD-L1 proteins in tumor tissues and adjacent tissues of NSCLC were detected by immunohistochemical staining." (PMID 36245982, 2022). "Our data using ten fresh-frozen tumor samples showed that in all GCTB tissues, there was similarly high relative phosphorylation of M-CSFR, InsR and PDGFRβ, as well as CREB and ERK1/2, independent of the treatment." (PMID 34298757, 2021). "miR-128 was shown to specifically inhibit insulin receptor (INSR) and insulin receptor substrate 1 (IRS1) to abate glycolytic signaling pathway and mitochondrial respiration, resulting in decreased tumor growth." (PMID 33824695, 2021). "Gong and colleagues found predominant InsR mitogenic isoform-A in GBM surgical specimens and xenograft tumor lines." (PMID 33604294, 2020). "Tumor cells with mesenchymal phenotype are resistant to the dual IGF-IR/InsR inhibitor linsitinib, due to the decreased expression of IGF2 and InsR, and phosphorylation of IGF-IR/InsR in these cells." (PMID 32493414, 2020).
tumor (continued). "This has a direct effect by increased binding of insulin to the tumour cell’s insulin-receptor and an indirect effect by increasing the concentration of free insulin-like-growth-factor-1 (IGF-1), resulting in increased tumour growth." (PMID 32210471, 2020). "EGFR, Insulin Receptor (INSR), and Vascular Endothelial Growth Factor Receptor (VEGFR), whose alternative splicing features variated, result in promoting tumor progression or reduced response to therapy." (PMID 31552163, 2019). "In vivo, insulin receptor (IR)/ insulin-like growth factor 1 receptor (IGF1R) signaling positively regulates fibroblast proliferation and activation, reducing tumor growth." (PMID 31014370, 2019). "The proliferation of the patient tumor cells (225ZL) was inhibited by arsenic trioxide (ATO), which is an inhibitor of the SHH pathway, by linsitinib, which is an inhibitor of IGF1R and INSR, and by ceritinib." (PMID 31480400, 2019). "Patients with tumors with both pIGF1R/InsRpos and IGF1Rstrong expression had a worse prognosis only when the tumor also expressed mod/strong levels of InsR, suggesting formation of IGF1R/InsR heterodimers." (PMID 28030849, 2017). "We so further quantified INSR/IGF1R phosphorylation, by RPPA on 97 tumors from the FBLAD-Exon tumor set." (PMID 28882129, 2017). "Analysis of tumor tissue lysates by phospho-RTK array showed a prominent tyrosine phosphorylation of EGFR, ERBB4, INSR and IGF1R in control which was remarkably decreased in tumor from treated mice." (PMID 27374103, 2016). "The pathophysiology of NICTH arises from excessive tumor production of both IGF-II and its precursor “big” IGF-II, resulting in an altered IGF-I to IGF-II ratio and insulin-independent stimulation of the insulin receptor." (PMID 27905899, 2016). "In SK-N-MC tumor xenografts, ERBB4 and EGFR were the prominent RTKs detected by the phospho-proteome array together with INSR and IGF1R." (PMID 27374103, 2016). "Insulin receptor activation can also stimulate the MEK/ERK1/2 MAPK (mitogen activated protein kinase) signaling pathway and contribute to tumor growth." (PMID 24858012, 2014). "Apart from promoting tumor growth, IGF1R and INSR overexpression also enhanced angiogenesis indicated by higher vessel density and increased number of desmin-immunoreactive pericytes." (PMID 24809298, 2014). "OSI-906 (Astellas Pharma Inc., Tokyo, Japan) is a potent, selective, orally bioavailable, dual IGF1R/INSR TKI, which has demonstrated in vivo efficacy in tumor models and is currently in clinical evaluation." (PMID 24904527, 2014). "Many tumour types have upregulated expression of IGF-1R, INSR, and potentially hybrid INSR/IGF-1Rs which facilitate increased activation of mitogenic, prosurvival and protein synthesis pathways with the increased levels of ligands insulin, IGF-1, or IGF-2." (PMID 22548055, 2012). "The compensatory upregulation of total and P-InsR upon inhibition of PI3K suggested that combined inhibition of InsR and PI3K would synergistically inhibit tumor cell viability." (PMID 22248929, 2011). "Apart from the complex TCR signalling in the tumour microenvironment, we wish to emphasize activation of the PI3K/AKT pathway which is mediated through a range of kinases in response to insulin receptor and insulin receptor substrate signalling." (PMID 39995112, 2025). "The expression of INSR, an evolutionarily conserved signaling protein that is downregulated upon relapse in AML patients, may be related to the inhibition of tumor cell growth and proliferation." (PMID 39213256, 2024). "Therefore, we further segregated ECs into tumor ECs (TECs) and normal ECs (NECs) using the TEC marker genes ENG, INSR, PECAM1, and SPRY1." (PMID 38182557, 2024). "The interactions where non-tumor cells influenced tumor cells included NAMPT → INSR, MIF → CD74 and CXCR4, GRN → SORT1, and CD99 → CD99." (PMID 39095793, 2024).
tumor (continued). "Also, IF staining revealed that CREB3 overexpression decreased IRS1 colocalization with INSR in HLF cells and LM3 cells, as well as in HLF subcutaneous tumor tissues." (PMID 38952575, 2024). "Finally, seven prognostic genes-ADH5, FAM162A, HS2ST1, INSR, G6PD, GLCE, and SDC3-were found to have the strongest correlation with tumor metastasis." (PMID 38586328, 2024). "A study with GSK1904529A shows that it potently reduces the phosphorylation of both IGF1R and InsR in vitro and in vivo, with no obvious effects on blood glucose levels at doses able to decrease tumor growth significantly." (PMID 37686528, 2023). "In our study, for the first time, INSR was expressed at lower abundance in non-tumorous (histologically normal) tissue and tumours compared with healthy samples." (PMID 36890818, 2023). "Furthermore, KIAA1324 has been reported to counteract insulin signaling by interacting with insulin receptor (INSR) and insulin-like growth factor 1 receptor (IGF1R) and inhibit cell proliferation, supporting the tumor-suppressive role of KIAA1324." (PMID 37612293, 2023). "Interestingly, INSR signaling has frequently been discussed as a possible compensatory mechanism for tumor cells when IGF1R is inhibited; however, these data suggest a positive correlation between IGF1R expression and INSR expression in human tumors." (PMID 35784559, 2022). "The sub‐clustering of ECs revealed six subtypes, including extra‐alveolar capillary EC (cEC) (FCN3+EDN1+PLVAP+), alveolar cEC (HPGD+EDNRB+IL1RL1+), arterial EC(GJA5+FBLN5+DKK2), lymphatic EC (CCL21+TFF3+FABP4), INSR+ tumour EC (INSRhiHSPG2+PLVAP+), and ACKR1+ tumour EC (ACKR1+SELP+IL1R1+)." (PMID 35184398, 2022). "These antibodies are species specific, and the HIRMAb does not recognize the mouse insulin receptor on the tumor vascular endothelium, which originates from mouse brain, and the 8D3 TfRMAb does not recognize the tumor cell human TfR [911,1043]." (PMID 35745855, 2022). "Therefore, we have reason to believe that INSR and IRS-1 are involved in the process of glycolysis metabolism and play an important role in maintaining the survival and proliferation of tumor cells." (PMID 36245982, 2022). "PREX1 activates insulin growth factor 1 receptor/insulin receptor signaling, as well as Rac1, phosphoinositide 3 kinase/protein kinase B, and mitogen-activated and extracellular-regulated kinase signaling, and PREX1 promotes cell and tumor viability." (PMID 32629428, 2020). "They assessed circulating interleukin-6 (IL-6), VEGF, fasting insulin, and tumor expression of insulin-like growth factor-1 receptor (IGF-1R), insulin receptor (IR), insulin-like growth factor-1 (IGF-1), and RAGE markers before surgery and 6 months after tumor surgery." (PMID 33117687, 2020). "Our comprehensive analysis of the expression of the insulin receptor in a large CRC cohort encompassing 1580 cases provides evidence that the IR is differentially expressed in both, tumor cells (EIR) and endothelial cells (VIR) of tumor vessels." (PMID 30680065, 2018). "Multivariable analysis revealed that pIGF1R/InsR did not provide independent prognostic information regarding event-free survival after adjustment for other prognostic factors and tumor storage time, HRadj (0.70; 95% CI 0.46-1.06)." (PMID 28030849, 2017). "On the one hand, ENPP4 may catalize the extracellular ATP released from tumor cells and reduce the binding between ATP and ATP receptor, on the other hand, ENPP4 may contact the insulin receptor and inhibit the insulin receptor activity." (PMID 26823374, 2016). "Tumor cells have been shown to develop alternative compensatory pathways to sustain cell proliferation, ultimately leading to drug resistance, such as HER3, IGF-1R, EGFR and insulin receptor pathways." (PMID 25762617, 2015). "Similarly to INSR, the mRNA expression of IRS1 is decreased in the tumour tissue compared to that in the control tissue (FDR = 2.62E-10)." (PMID 25496518, 2014).
tumor (continued). "However, combined treatment with AZD5363 and the InsR/IGF-IR inhibitor AZD9362 was significantly superior to AZD5363 alone (P = 0.004), inducing a complete tumor regression in one mouse." (PMID 23844554, 2013). "The relative increased expression of INSR (a receptor for insulin) and IGF1 in the resistant cohort in our study indicates that the drug resistant cells evolve multiple compensatory mechanisms for tumour cell survival." (PMID 24237932, 2013). "Interestingly, hyperglycaemia in the absence of hyperinsulinemia has not been reported to provoke tumor growth in animal models, depicting the role of insulin receptor activation." (PMID 34535145, 2021). "Interestingly, the expression of the fetal insulin receptor has been reported to be increased in CRC and liver cancer and would contribute with other genetic and environmental factors to the development of these neoplasias." (PMID 31207998, 2019). "Further mechanisms of tumor suppression by TZDs may involve the inhibition of important target genes, such as the vascular endothelial growth factor, VEGF, gene, the PGE2 receptor gene, and the insulin receptor gene." (PMID 30123711, 2018). "Targeting of all three receptors may be more efficient since dual inhibition of InsR and IGF1R with tyrosine kinase inhibitor OSI-906 in combination with ER downregulator fulvestrant more effectively suppress hormone-independent tumor growth than either drug alone." (PMID 29234306, 2017). "This might indicate that the IRA plays a stimulatory role in the transformation of normal to neoplastic MG tissue, but once the MG tumor is established the A isoform of the insulin receptor does not play a key role in proliferative signaling anymore." (PMID 28173837, 2017). "The fact that insulin receptor signalling can stimulate protein synthesis and inhibit apoptosis and the fact that IGF-1 receptor signalling enhances cell proliferation explain how hyperinsulinaemia and increased IGF-1 may result in tumour growth." (PMID 27795741, 2016). "Angiogenesis-related genes (FLT1, KDR, SPARC, INSR, ANGPT2, and FLT4) and MHC-I molecules (HLA-A, HLA-B, HLA-C, HLA-E, and HLA-F) were highly expressed in cluster 3 ECs, indicating that the cells may function as antigen-presenting cells and promote tumor parenchymal angiogenesis." (PMID 37533434, 2023). "Interfering with insulin signaling may slow tumor growth, while activation of the insulin receptor may promote tumor progression in murine models, although there have also been publications demonstrating the absence of an effect of insulin on tumor growth." (PMID 31867105, 2019). "Expression of INSR, but not IGF1R, was significantly higher in tumour than in normal gastric tissue." (PMID 34554347, 2022). "Thus, the C. vasculum compound 1 binds to IGF-1Rβ but not InsR or EGFR in NSCLC cells, and both compounds 1 and 2 impair IGF-1Rβ phosphorylation and cause IGF-1Rβ degradation thereby impairing oncogenic signaling in tumor cells resulting in prominent cell death." (PMID 27384680, 2016). "In line with the in vitro data overexpression of IGF1R and INSRA but not INSRB significantly increased tumor area, while downregulation of the IGF1R and the INSR strongly reduced tumor growth in the CAM-assay." (PMID 24809298, 2014). "This suggests that binding to IGF‐1R alone is not sufficient for a good antitumor response and that in tumor cells the PI3K/MAPK pathway may remain activated, possibly also through InsR." (PMID 31490549, 2020).